SOST (sclerostin)
Diseases named in the same sentence as SOST in open-access papers (continued):
Sharing a sentence is not in itself a finding about the gene and the disease.
Obesity (continued). "We conclude that deranged liver function leads to raised sclerostin levels in men affected by alcohol overuse; these raised sclerostin levels are related to obesity and gynoid and android fat accumulation." (PMID 35807755, 2022). "In conclusion, baseline serum levels of sclerostin correlate with anthropometric measures of obesity and insulin resistance and can predict glycemic improvements after SG." (PMID 33671861, 2021). "The aim of this study was to investigate the relationship between sclerostin and anthropometric and metabolic parameters in children and adolescents with obesity or who are overweight." (PMID 34572220, 2021). "In conclusion, baseline serum levels of sclerostin correlate with anthropometric measures of obesity and IR, and the ability to predict glycemic improvements after SG." (PMID 33671861, 2021). "Given the mild difference in sclerostin levels between pre- and postmenopausal women, its potential actions in obesity require further investigation." (PMID 34679612, 2021). "While we did not observe any differences in inflammation between ObAF and NwAF, there is an influence of obesity on the regulation of sclerostin post-exercise." (PMID 33362710, 2020). "Similarly, in younger women (< 50 years old), high sclerostin levels correlated with obesity, but in contrast to older postmenopausal women, sclerostin correlated negatively with spine and femoral neck BMD and the trabecular bone score." (PMID 38625510, 2024). "The relationship between obesity and circulating SOST levels is unclear in the literature." (PMID 38711986, 2024). "More studies are required to clarify the role of sclerostin in the pathogenesis of obesity." (PMID 36145151, 2022). "Similarly, in children with obesity, sclerostin concentrations were decreased compared with the control group, and correlated negatively with BMI." (PMID 36145151, 2022). "The only variable which showed an independent relationship with sclerostin was obesity (p = 0.015)." (PMID 35807755, 2022). "Finally, in pre- and postmenopausal women with obesity sclerostin positively predicted lumbar spine BMD." (PMID 35873004, 2022). "Sclerostin and bone-regulating hormones: Being a factor that promotes bone resorption, we evaluated sclerostin and its regulation operated by perimenopausal hormone status so as to identify potential modulators of bone status in obesity." (PMID 34679612, 2021). "Obesity has been shown to increase levels of the Wnt inhibitors SOST and DKK1." (PMID 27746742, 2016). "Therefore, sclerostin was significantly related to obesity and liver function." (PMID 35807755, 2022). "This comprehensive study conducted in severely obese women distinguished by menopause provides evidence that obesity does not associate with (early) postmenopausal bone loss at the lumbar spine, with sclerostin acting as the strongest protective determinant at this site." (PMID 34679612, 2021). "Remarkably, preoperative SOST and DKK1 levels in patients with obesity were the highest among study participants." (PMID 40732944, 2025). "In a cross-sectional study involving 240 healthy subjects from the Korean Sarcopenic Obesity Study (KSOS), the authors found that circulating sclerostin levels correlated negatively with ALM." (PMID 36982995, 2023). "The aim of the study was to determine the effects of 12-week supervised SIT on serum osteocalcin, lipocalin-2 and sclerostin levels, bone mineral density (BMD) and bone mineral content (BMC) characteristics in adolescent boys with obesity." (PMID 37238398, 2023). "The patients with obesity showed the lowest SIRT1 and TBS values and the highest sclerostin concentrations; BMD increased with FM and BMI and had an inverse association with SIRT1." (PMID 35267956, 2022). "In addition, sclerostin may contribute towards atherosclerosis, obesity and insulin resistance." (PMID 36145151, 2022).
Obesity (continued). "In conclusion, we found that serum sclerostin level was negatively correlated with HOMA–IR in children and adolescents with obesity." (PMID 34572220, 2021). "We also showed that obesity does not affect circulating SOST levels, as shown by the lack of correlation and the results of the quantile regression." (PMID 38711986, 2024). "We hypothesize that Individuals with obesity and T2DM will have higher circulating levels of SOST compared to healthy individuals." (PMID 38711986, 2024). "While some studies indicate a rise in serum SOST levels with obesity, others have not identified such a link." (PMID 38711986, 2024). "Bone turnover markers, sclerostin, periostin and semaphorin 4D were assessed before and 1, 12 and 24 months after SG, and aBMD was determined by DXA at baseline and after 12 and 24 months in 83 patients with obesity." (PMID 37892386, 2023). "Supervised 12-week SIT intervention improved bone mineral characteristics, but did not change osteocalcin, lipocalin-2 or sclerostin levels in adolescent boys with obesity." (PMID 37238398, 2023). "Obesity, defined according to BMI, and body fat were strongly related to sclerostin, being independent of serum creatinine and of liver function." (PMID 35807755, 2022). "BMI was the strongest predictor of BMD in our cohort, despite the lower levels of SIRT1 and the higher levels of sclerostin seen in the group of patients with obesity should have predicted a negative effect on bone." (PMID 35267956, 2022). "The primary purpose of this pilot study was to measure circulating sclerostin and examine scWAT for changes in sclerostin content and Wnt signaling (β‐catenin accumulation) following 4 weeks of sprint interval training (SIT) in young men with obesity." (PMID 35312183, 2022). "Our lab has also shown that normal weight healthy children have no response of circulating sclerostin to acute exercise, while those with obesity have an adult-like, transient post-exercise increase." (PMID 36685192, 2022). "Another study of children and adolescents with obesity reported a negative correlation of sclerostin level with both fasting insulin and HOMA-–IR." (PMID 34572220, 2021). "Matrix Gla protein (MGP), Noggin, Sclerostin (SOST), and Gremlin have been identified as several extracellular, intracellular and transcriptional BMP inhibitors that are upregulated in obesity and act as negative regulators of BMP signaling pathways, ultimately downregulating osteoblastogenesis." (PMID 27746742, 2016). "Moreover, obesity would alter levels of numerous molecules, such as TNFα, DKK1, sclerostin, IL-6, serotonin, and advanced glycation end products, which could inhibit osteoblastogenesis." (PMID 40685394, 2025). "Moreover, the significantly better TBS of underweight patients compared to patients with obesity could be interpreted as more evidence in support of the beneficial effect of high SIRT1 and low sclerostin pattern on bone microarchitecture and quality." (PMID 35267956, 2022). "We speculate that the negative control exerted by testosterone on sclerostin levels is peculiar of obesity and likely due to enhanced fat-derived androgen aromatization." (PMID 34679612, 2021). "Thus, future clinical trials should examine the response of adiposity to sclerostin neutralizing antibody treatment with and without exercise training in individuals with obesity and metabolic syndrome to separate the exercise induced responses from those of such treatment in humans." (PMID 35312183, 2022).
periodontitis (34 papers, 2016 to 2026). An acute or chronic inflammatory process that affects the tissues that surround and support the teeth. "Therapeutically, sclerostin inhibition demonstrates robust preclinical efficacy in rescuing bone loss in models of periodontitis and estrogen deficiency." (PMID 41636271, 2026). "The periodontitis-linked SNP rs9783823 displayed a significant cis-activating effect (25-fold change in SOST expression), with the C-allele containing a CEBPB binding motif (position weight matrix (PWM) = 0.98, Pcorrected = 7.7 x 10-7)." (PMID 40127057, 2025). "Continued exploration of the molecular mechanisms underlying sclerostin inhibition will further inform the development of therapeutic strategies against periodontitis and tooth loss." (PMID 39171525, 2024). "Sclerostin, a secreted glycoprotein generated by osteocytes and encoded by the SOST gene, was found to be highly expressed inGCF ofC\chronic periodontitis patients compared to healthy patients." (PMID 36902030, 2023). "In this context, the glycoprotein sclerostin, encoded by the SOST gene, has emerged as a new research topic for periodontitis treatment." (PMID 37108735, 2023). "In a ligature-induced periodontitis study, an increased expression of SOST was associated with reduced bone formation, while increased bone formation was accompanied by a reduced expression of SOST-positive osteocytes." (PMID 34440994, 2021). "Periodontitis-mediated inflammation causes sclerostin production and NF-κβ activation in alveolar osteocytes." (PMID 32733380, 2020). "Taken together, the results of this clinical study suggest both sclerostin and Wnt proteins as a promising diagnostic tool for periodontitis." (PMID 33732211, 2020). "In summary, these results indicate that intermittent PTH administration increases osteoid formation and mineralization, and diminishes alveolar bone loss and sclerostin expression in osteocytes of type 1 diabetic rats with periodontitis." (PMID 29544500, 2018). "Clinical studies verified the results obtained from the animal studies regarding the involvement of sclerostin in alveolar bone loss associated with periodontitis." (PMID 30477095, 2018). "Osteocytic sclerostin expression has been linked to alveolar bone resorption during suppressed bone formation in rats with ligature-induced periodontitis." (PMID 30477095, 2018). "Animal trials showed that removal of SOST or blocking the expression of sclerostin reduces significantly bone loss associated with periodontitis in mouse models." (PMID 30477095, 2018). "In periodontitis, alveolar bone loss can be countered using a pharmacotherapeutic if sclerostin therapy proves efficacious." (PMID 30477095, 2018). "Targeting the SOST gene has been identified as a treatment for bone disorders including osteoporosis, and bone loss as the result of periodontitis." (PMID 29457146, 2017). "Taken together, these findings suggest that RANKL and sclerostin expression is involved in alveolar bone loss in periodontitis." (PMID 29240821, 2017). "Our previous published researches demonstrated that sclerostin was involved in alveolar bone loss in periodontitis and occlusal hypofunction." (PMID 28081119, 2017). "This study examined the relationship between gingival crevicular fluid (GCF) and serum sclerostin and PGE2 levels and the inflammatory bone resorption associated with chronic apical periodontitis (AP) as well as the correlation between sclerostin regulation and RANKL and MMP-9 levels." (PMID 40323540, 2026). "Below, the recently elucidated role of osteocytes in the pathogenesis of periodontitis is discussed, highlighting RANKL and sclerostin secretion, osteocyte senescence, osteocyte apoptosis, and their potential effect on the association of periodontitis with systemic disease." (PMID 33308247, 2020). "The authors considered that the local inflammatory microenvironment in periodontitis may overcome the systemic osteoclast inhibition caused by sclerostin inhibition." (PMID 33308247, 2020).
periodontitis (continued). "Sclerostin gene knockout also attenuates alveolar bone loss in mice with periodontitis." (PMID 32708317, 2020). "In animal experiments, an increase in sclerostin-positive osteocytes within alveolar bone was linked to a decrease in bone formation in a mouse model of periodontitis; in parallel, the administration of sclerostin- and DKK1-specific antibodies markedly improved alveolar bone volume and structure." (PMID 33308247, 2020). "Since anti-sclerostin improves the periodontal status and RANKL expressed by osteocytes causes periodontitis, it could be that sclerostin influences RANKL and thereby the catabolic nature of osteocytes." (PMID 30924022, 2019). "This may reinforce the hypothesis of the role of osteocytes as source of sclerostin during periodontitis-induced alveolar bone loss." (PMID 30477095, 2018). "The involvement of sclerostin in the inflammatory process associated with periodontitis and resulting in alveolar bone loss made many researchers to investigate the effect of the sclerostin antibody (Scl-Ab) on bone healing and the management of alveolar bone loss associating periodontitis." (PMID 30477095, 2018). "Therefore, TNF-α might mediate alveolar bone loss via inducing expression of osteocytic RANKL and sclerostin in type 1 diabetes rats with periodontitis." (PMID 29240821, 2017). "This study identifies a robust SOST cis-activating element linked to BMD and periodontitis, carrying CEBPB binding sites, and highlights CEBPB’s impact on epithelial-mesenchymal transition." (PMID 40127057, 2025). "A haplotype block at the sclerostin (SOST) gene correlates with bone mineral density (BMD) and increased periodontitis risk in smokers." (PMID 40127057, 2025). "Two studies showed that sclerostin levels were significantly higher in periodontitis patients compared to controls." (PMID 39410587, 2024). "Furthermore, studies suggest that elevated levels of sclerostin in CKD increase the progression of periodontitis by inhibiting bone remodelling and therefore, elevated sclerostin levels secondary to CKD-MBD may potentiate periodontitis-related alveolar bone loss." (PMID 38541146, 2024). "Wnt signaling, due to its well-established role in bone homeostasis and periodontal tissues regulation, as well as its inhibitors DKK-1 and sclerostin have recently shown potential as therapeutic targets for periodontitis." (PMID 38541234, 2024). "With the discovery of positive sclerostin expression in PDLCs, its role in periodontitis has recently become a popular subject to explore." (PMID 35562828, 2022). "Clinical studies have shown that sclerostin level is higher in the gingival tissue, gingival crevicular fluid and serum of patients with chronic periodontitis than in healthy people, and is accompanied by an increased RANKL production." (PMID 35562828, 2022). "In periodontitis, the synthesis of sclerostin increases related to the activation of the inflammatory cascade." (PMID 35806779, 2022). "The detection of sclerostin level and the application of Scl-Ab offer great potential for the diagnosing and treating periodontitis." (PMID 35562828, 2022). "SOST trended higher in the GCF of gingivitis sites but similar in chronic periodontitis and healthy sites." (PMID 34440994, 2021). "Although periodontitis and healthy sites demonstrated similar Sclerostin amounts in GCF, gingivitis sites exhibited a trend towards higher amounts." (PMID 34440994, 2021). "Antagonizing TNF-α using infliximab reduces expression of sclerostin and RANKL in osteocytes and the alveolar bone loss in diabetic rats with periodontitis." (PMID 32708317, 2020). "In adults with moderate to severe periodontitis, a significant increase of sclerostin in the GCF was determined when compared with healthy patients." (PMID 33732211, 2020). "Evidence related to the effects of periodontitis bacteria and their toxic substances on sclerostin production in osteocytes is insufficient." (PMID 33308247, 2020).
periodontitis (continued). "The sclerostin content in gingival crevicular fluid from chronic periodontitis patients markedly exceeds that of healthy subjects, and the protein levels of sclerostin and DKK1 in gingival biopsy tissue and serum are relatively increased." (PMID 33308247, 2020). "Diabetic rats with periodontitis show a higher expression of sclerostin, RANKL, tumor necrosis factor-α (TNFα), and IL-1β in osteocytes, which affects osteoblast and osteoclast function." (PMID 32733380, 2020). "These rats developed periodontitis within 4 weeks and after removal of the silk sutures, animals were treated with an antibody against sclerostin." (PMID 30924022, 2019). "Antibodies against the osteocyte-derived protein sclerostin inhibit and partially revert periodontitis by stimulating bone formation." (PMID 30924022, 2019). "TNF-α has been shown to upregulate sclerostin expression in MLO-Y4 cells; consistent with this finding, the use of a TNF-α antagonist was able to diminish RANKL and sclerostin expression in the osteocytes of diabetic rats with periodontitis." (PMID 31341915, 2019). "This review will modify this view by including the recently elucidated role of RANKL and sclerostin expressing osteocytes in the pathogenesis of periodontitis." (PMID 30924022, 2019). "When inducing periodontitis, the sclerostin knockout mice were slightly protected compared to wild-type mice." (PMID 30924022, 2019). "Blocking SOST by application of a SOST-specific antibody enhances healing of alveolar bone in experimental periodontitis (Chenet al., 2015;Liuet al., 2018;Tautet al., 2013)." (PMID 31031968, 2019). "In previous studies of rats with periodontitis, treatment with sclerostin antibodies was found to induce an anabolic response during alveolar bone healing by increasing bone formation." (PMID 29544500, 2018). "Sclerostin and sclerostin-RANKL ratio was found to be significantly lower in gingival crevicular fluid samples of healthy individuals than with patients with periodontitis." (PMID 30477095, 2018). "We have previously found that osteocytic sclerostin expression is inversely related to osteoid formation in rats with periodontitis." (PMID 29240821, 2017). "To determine the effect of IFX on osteocytic sclerostin expression in type 1 diabetes with periodontitis, we counted the number of sclerostin-positive osteocytes and measured sclerostin mRNA expression in alveolar bone of the distal area." (PMID 29240821, 2017). "The objective of this study was to determine the effect of TNF-α expression of osteocytic RANKL and sclerostin in type 1 diabetes rats with periodontitis using infliximab (IFX), a TNF-α antagonist." (PMID 29240821, 2017). "Patients with chronic periodontitis have higher sclerostin levels in gingival tissues and serum than non-periodontitis individuals, suggesting a possible role of sclerostin in periodontal tissues." (PMID 29240821, 2017). "In a recent study, we found a common haplotype block in the genetic region of SOST, which was associated with BMD (rs1513670) and severe periodontitis (classified as periodontitis stages III/IV, grade C; PIII-IV/C) diagnosed in young adults (rs6416905, linkage disequilibrium r2 > 0.8)." (PMID 40127057, 2025). "Increased expression of sclerostin in GCF in patients with periodontitis indicated that it could be considered a reliable biomarker of periodontal disease activity." (PMID 37645545, 2023). "However, a slight increase in the GCF levels of sclerostin was observed in patients with periodontitis.Patients with periodontitis had increased levels of SOST expression in their gingival tissue samples compared to healthy individuals." (PMID 37645545, 2023). "Thus, it can be seen that sclerostin in alveolar osteocytes plays a crucial role in alveolar bone formation during periodontitis." (PMID 35562828, 2022). "Accordingly, as a potential regulator of periodontitis, sclerostin may also exert a pro-inflammatory effect on peri-implant diseases." (PMID 35562828, 2022).